PRDM16 (PR/SET domain 16)
Diseases named in the same sentence as PRDM16 in open-access papers (continued):
Sharing a sentence is not in itself a finding about the gene and the disease.
psoriasis (2 papers, 2022 to 2023). An autoimmune condition characterized by red, well-delineated plaques with silvery scales that are usually on the extensor surfaces and scalp. "Supporting this, we showed that Prdm16 deficiency was associated with pathogenesis of severe psoriasis in mice." (PMID 38239368, 2023). "Specifically, loss of Prdm16 exacerbates development of psoriasis in the skin, a lipid-rich organ, and Prdm16 controls lipid-mediated differentiation of Vγ4+ γδT17 cells, which are the major source of IL-17 during the onset of psoriasis." (PMID 38239368, 2023). "For further verification, we found that the expression of TRIM14 mRNA increased and PRDM16 mRNA decreased in PBMC of psoriasis patients by RT-PCR and the protein expression detected by ELISA showed the same trend." (PMID 36193156, 2022). "DNA methylation sequencing results suggest that TRIM14 is hypomethylated in psoriasis, whereas PRDM16 is hypermethylated." (PMID 36193156, 2022). "Given that Vγ4+ γδT17 cells are the major source of IL-17 during psoriasis, this could also explain the exacerbation of psoriasis in Prdm16 cKO mice." (PMID 38239368, 2023). "Since we observed exacerbated psoriasis in Prdm16 cKO mice, we hypothesized that Prdm16 might control the differentiation of Vγ4+ γδT17 cells." (PMID 38239368, 2023). "Our study found that methylation levels of genes TRIM14 and PRDM16 may be important markers of psoriasis severity, but the specific mechanism of action of these associated genes requires further research." (PMID 36193156, 2022). "In addition, DNA methylation levels of TRIM14 and PRDM16 may serve as potential biomarkers for assessing the severity of psoriasis." (PMID 36193156, 2022). "Therefore, we speculate that DNA methylation modifications are involved in the expression of TRIM14 and PRDM16 in psoriasis." (PMID 36193156, 2022). "Therefore, PRDM16 may play an important role in the pathogenesis of psoriasis." (PMID 36193156, 2022). "In the correlation analysis between DNA methylation level and psoriasis severity, we found that TRIM14 gene was significantly and negatively correlated, while PRDM16 gene was significantly and positively correlated." (PMID 36193156, 2022). "We also found that the methylation levels of TRIM14 and PRDM16 were closely correlated with PASI scores and could serve as potential biomarkers to assess the severity of psoriasis." (PMID 36193156, 2022). "In the correlation analysis between psoriasis methylation level and PASI score, the highest negative correlation was TRIM14, and the highest positive correlation was PRDM16." (PMID 36193156, 2022).
T-cell acute lymphoblastic leukaemia (2 papers, 2008 to 2024). "In B cells, PRDM16 and DNMT3A for AML, PDCD1LG2 for Hodgkin’s lymphoma, LMNA for spritzed tumor, and BCL11B for T-cell acute lymphoblastic leukemia (T-ALL) harbored DMPs for HIV infection." (PMID 38466776, 2024).
aging (1 paper, 2025). A developmental process that is a deterioration and loss of function over time. "In this study, we elucidated the anti‐senescence role of PRDM16 and its underlying mechanism, providing a potential target for mitigating aging and aging‐related diseases." (PMID 40946183, 2025).
alcoholic cirrhosis (1 paper, 2024). "Further UMAP analysis indicated that the expression levels of genes such as PRDM16 and WWTR1 were elevated in alcoholic cirrhosis patients, while other genes like C18orf63 and RNU6ATAC39P showed decreased expression." (PMID 39588518, 2024).
Alzheimer disease (1 paper, 2024). A progressive, neurodegenerative disease characterized by loss of function and death of nerve cells in several areas of the brain leading to loss of cognitive function such as memory and language. "Since adult hippocampal neurogenesis is impaired during aging and neurodegenerative diseases such as Alzheimer’s diseases, targeting Prdm16 could be a novel approach to enhance plasticity in the diseased brain." (PMID 38217668, 2024).
and non-compaction cardiomyopathy (1 paper, 2024). "Mutation of the PRDM16 gene causes human dilated and non-compaction cardiomyopathy." (PMID 37842925, 2024).
angina (1 paper, 2025). "Notably, the CpG site cg01065697, located in the PRDM16 gene, was significantly associated with the risk of MI, CHD, and angina simultaneously." (PMID 41420191, 2025).
aortic aneurysm (1 paper, 2023). A ruptured aneurysm located in the wall of the proximal portion of the descending aorta proceeding from the arch of the aorta. "Although currently there are no available agonists for PRDM16, it has been shown that PPARγ agonists could potently increase the half-life of the PRDM16 protein and PPARγ agonists attenuate inflammation in aortic aneurysm patients." (PMID 37079380, 2023).
arterial disorder (1 paper, 2025). An impairment of the structure or function of the blood vessels which carry blood away from the heart. "Together, these studies suggest that PRDM16 protects against arterial disorders via its effect on ECs, PVAT cells, and SMCs, and that loss of PRDM16 invariably leads to transcriptional changes with associated pathogenic, maladaptive cell states that contribute to disease progression." (PMID 40439125, 2025). "Moreover, as PRDM16 is expressed in multiple cell types involved in arterial disease, reduced PRDM16 levels likely perturb the cross-talk between ECs, SMCs, and PVAT cells, with detrimental consequences for arterial health and function." (PMID 40439125, 2025).
asthma (1 paper, 2022). "Significant DMPs fall within genes involved in the TFG-β related pathways (e.g. BMP2, FLCN, ING2, PMEPA1, PRDM16, TGFB1I1 and TGFBR3), in line with previous studies that reported an association between these genes and the increased asthma risk." (PMID 35619695, 2022).
autism spectrum disorder (1 paper, 2022). A spectrum of developmental disorders that includes autism, and Asperger syndrome. "For example, Slc1a2, Prdm16, Kank1 and Ddah1 were target genes of Dbx2, the high expression of Slc1a2 was found to reduce the risk for PD in a Chinese cohort and the other genes are associated with cognitive function, autism spectrum disorder and depression-like behavior, respectively." (PMID 36142685, 2022).
autoimmune disease (1 paper, 2025). A disorder resulting from loss of function or tissue destruction of an organ or multiple organs, arising from humoral or cellular immune responses of the individual to their own tissue constituents. "It is suspected that PRDM16 may restrict autoimmune disease by protecting regulatory T cells." (PMID 40758676, 2025).
cataract (1 paper, 2023). Partial or complete opacity of the crystalline lens of one or both eyes that decreases visual acuity and eventually results in blindness. "Importantly, the present analyses identify as yet unappreciated and novel high-priority candidates in the lens for defining new pathways involved in lens biology (e.g., Ell2 and Prdm16) that likely also contribute to the cataracts resulting from Celf1 deficiency." (PMID 37048143, 2023).
colitis (1 paper, 2021). Inflammation of the colon. "DSS-induced colitis mice showed significantly decreased expressions of PPARα, PGC-1α, and thermogenic genes including ND5, Prdm16, Cidea, Elovl3, Dio2, and UCP1 both in SAT and BAT compared to non-colitis control mice." (PMID 33674694, 2021).
congenital heart disease (1 paper, 2024). A heart disease that is present at birth. "Remarkably, previous studies identified the deletion of Prdm16 expression in human embryos with congenital heart disease." (PMID 38542214, 2024).
depression (1 paper, 2021). "Bayesian relevance analysis confirmed the relevance of intergenic rs6660757 and rs12128399 (p31.1), rs1043215 (REST), rs1889974 (HPSE2) and rs11163394 (ADGRL2) from depression interaction results, and the moderate relevance of rs77864828 and rs2455107 of PRDM16 from main effect analysis." (PMID 34972135, 2021).
diabetic retinopathy (1 paper, 2017). "In this study, we found that CpG methylation regulates pathways that are used as pharmacological targets in diabetic retinopathy progression, such as angiogenesis (ETS1, HES5, PRDM16)." (PMID 28924151, 2017).
dwarfism (1 paper, 2021). "We report bantam‐associated genes in these group‐based studies, including HMGA2 and PRDM16, some of them are reported to correlate with dwarfism in chicken for the first time." (PMID 33897823, 2021).
Fanconi Anaemia (1 paper, 2022). "These include variants in genes encoding FANCE, a subunit of the Fanconi Anaemia (FA) nuclear complex; NKX2-1, a transcription factor and negative regulator of the NF-κB signalling pathway; and other recognized oncogenes JAK2, PRDM16, BMPR1A and tumor-suppressor genes KMT2C, FAT4, and LRP1B." (PMID 35954343, 2022).
gastric adenocarcinoma (1 paper, 2020). "Additionally, exosomes from SGC7091 (gastric adenocarcinoma) cells had a higher expression ciRS-133, and when added into the medium of 3T3L1 cells, induced upregulation of PR-domain containing 16 (PRDM16) and UCP1." (PMID 32325796, 2020).
gestational diabetes (1 paper, 2020). Carbohydrate intolerance first diagnosed during pregnancy. "Epigenetic regulation of Prdm16 through DNA methylation modification has also been demonstrated in peripheral blood of adolescents exposed to maternal diabetes in utero, the placenta of mothers with gestational diabetes, and in connection to cancer." (PMID 32059412, 2020).
hypertrophic cardiomyopathy (1 paper, 2022). A condition in which the myocardium is hypertrophied without an obvious cause. "We and others have demonstrated that a loss in PRDM16 causes hypertrophic cardiomyopathy, leading to HF." (PMID 35862303, 2022). "We have previously shown that the loss of Prdm16 in mouse heart causes hypertrophic cardiomyopathy and a failure in cardiac conduction." (PMID 35862303, 2022). "Our cardiac-specific Prdm16-null mouse developed hypertrophic cardiomyopathy and had low BP, strengthening it as a mouse model of HF and hypotension." (PMID 35862303, 2022).
hypothyroidism (1 paper, 2022). Abnormally low levels of thyroid hormone. "In BAT, we found reduced Klf9 (−34.82%) expression and 2.51-fold increased mRNA levels of Ucp1, the master regulator of brown adipocyte thermogenesis, although Prdm16, the transcriptional coregulator of brown adipocyte differentiation, and Ppargc1a were not regulated by hypothyroidism." (PMID 36143246, 2022).
kidney tumors (1 paper, 2022). "The results of Oncomine revealed that both MECOM and PRDM16 expression were downregulated in lung, breast, gastric, sarcoma, and kidney tumors compared with normal tissues (all p < 0.05)." (PMID 35174083, 2022).
leiomyosarcoma (1 paper, 2020). An uncommon, aggressive malignant smooth muscle neoplasm, usually occurring in post-menopausal women. "Otherwise, array-CGH integrated with gene expression analysis of leiomyosarcoma revealed a frequent loss at 1p36, which contains PRDM16, suggesting that this defect could promote muscle differentiation in this context." (PMID 32290321, 2020). "Similarly, integrated analysis of uterine leiomyosarcoma revealed PRDM16 deletions and/or reduced expression." (PMID 32290321, 2020).
leukocytosis (1 paper, 2020). "Although both have a paradoxical behavior in tumorigenesis our data indicates that KIAA0125 and PRDM16 may act as oncogene, once amplifications in these two genes were related to gene fusions and leukocytosis, respectively." (PMID 32607130, 2020).
Lissencephaly (1 paper, 2024). A spectrum of malformations of cortical development caused by insufficient neuronal migration that subsumes the terms agyria, pachygyria and subcortical band heterotopia. "A significant breakthrough came with the discovery ofa patient carrying a unique PRDM16 gene mutation linked to lissencephaly andmicrocephaly." (PMID 38595939, 2024). "We report a patient with a de novo nonsensemutation in the PRDM16 coding sequence, accompanied by lissencephaly and microcephalyfeatures." (PMID 38595939, 2024).
myocardial disease (1 paper, 2020). "PRDM16 (histone-lysine N-methyltransferase PRDM16) functions as a transcriptional regulator and a previous study confirmed a causal role for this locus in human myocardial disease." (PMID 31999706, 2020).
overnutrition (1 paper, 2021). An imbalanced nutritional status resulting from excessive intake of nutrients. "Therefore, accompanied by lower levels of UCP1, PRDM16, and PGC1α mRNAs in HIGH fetuses, it is suggested that the manipulation of maternal nutrition, especially long-term maternal overnutrition, might adversely affect brown adipose tissue mass and its function in adipose depots of the fetus." (PMID 35178028, 2021).
pancreatic ductal adenocarcinoma (1 paper, 2025). An infiltrating adenocarcinoma that arises from the epithelial cells of the pancreas. "A recent study similarly reported that PRDM16 acts as a SMAD4 co-repressor during pancreatic ductal adenocarcinoma progression." (PMID 40658097, 2025).
Papillary Thyroid Cancer (1 paper, 2021). "PRDM16 was downregulated in papillary thyroid cancer tissues and was significantly related with lymph node metastases and extrathyroidal extension in both FUSCC and TCGA cohorts." (PMID 34796170, 2021). "PRDM16 may be a novel therapeutic target in papillary thyroid cancer." (PMID 34796170, 2021). "It is not clear yet whether PRDM16 is involved in tumor progress of papillary thyroid cancer (PTC)." (PMID 34796170, 2021).
peripheral artery disease (1 paper, 2023). "A recent study revealed that PRDM16 is highly expressed in arterial endothelial cells and smooth muscle cells (SMCs), and that PRDM16 in endothelial cells but not SMCs is indispensable for normal arterial blood flow recovery in peripheral artery disease." (PMID 37079380, 2023).
prediabetes (1 paper, 2019). "Accordingly, IL-33 was directly associated with PRDM16 but not with UCP1 or COX7A1 in individuals with normoglycemia and T2D but not in those with prediabetes." (PMID 31073344, 2019).
prolymphocytic leukemia (1 paper, 2025). A mature B- or T- cell leukemia with progressive clinical course. "The presence of the PRDM16::SKI fusion gene was described, for the first time, in a T prolymphocytic leukemia (T-PLL) patient with a long indolent period and a late development treatment requiring disease." (PMID 40933896, 2025).
rotator cuff tears (1 paper, 2024). "Overexpression of PRDM16 significantly improved muscle function and reduced fatty infiltration after rotator cuff tears." (PMID 39032686, 2024). "More work is needed to see the effects of PRDM16 overexpression in acute rotator cuff tears along with immediate and delayed repair of the rotator cuff." (PMID 39032686, 2024). "In this study, we used our rotator cuff injury mouse model that replicates the fibrosis and fatty infiltration frequently seen in patients with rotator cuff tears to assess the impact of overexpression of PRDM16 on muscle quality and recovery." (PMID 39032686, 2024).
schizophrenia (1 paper, 2022). A major psychotic disorder characterized by abnormalities in the perception or expression of reality. "Some of the connected genes like PRKCZ, SHANK2, ZNF608, and PRDM16 were also identified as schizophrenia risk factors." (PMID 36259657, 2022).
Sinus bradycardia (1 paper, 2022). Bradycardia related to a mean resting sinus rate of less than 50 beats per minute. "Among those who developed symptoms of HF (LVEF reduction and LV enlargement) were patients P9 (novel pathogenic PRDM16 complex rearrangement c.1286_1289delinsTTGCACTT p.(Gly429Valfs*176)) and P7 with additional sinus bradycardia (novel likely pathogenic MYH7 c.3973-2A>C p.?" (PMID 35893073, 2022).
thyroid cancer (1 paper, 2026). "Collectively, these findings establish PRDM16 as a novel tumor suppressor and potential therapeutic target, offering a promising redifferentiation-based strategy for the treatment of advanced thyroid cancer." (PMID 42157931, 2026). "In this study, we identify PRDM16 as an essential regulator of thyroid cancer differentiation." (PMID 42157931, 2026).
viral infection (1 paper, 2025). "This failure was likely due to low viral production (the Prdm16 coding sequence exceeds 3 kb) and the increased sensitivity of KO NSCs to viral infection." (PMID 40658097, 2025).